CTLA4 (cytotoxic T-lymphocyte associated protein 4)
Diseases named in the same sentence as CTLA4 in open-access papers (continued):
Sharing a sentence is not in itself a finding about the gene and the disease.
tumor (continued). "To date, several immune checkpoint inhibitors (ICIs) have been approved for tumor treatment, including PD-1 inhibitors (nivolumab, pembrolizumab, cemiplimab), PD-L1 inhibitors (avelumab, durvalumab, atezolizumab), and CTLA-4 inhibitors (ipilimumab)." (PMID 38283361, 2023). "ICIs, such as monoclonal antibodies targeting PD-1 (pembrolizumab, nivolumab), PD-L1 (atezolizumab, durvalumab, avelumab), and CTLA-4 (ipilimumab), have resulted in long-term responses in numerous tumor types." (PMID 36900322, 2023). "Antibodies targeting programmed cell death 1 (PD-1), programmed cell death ligand 1 (PD-L1), and cytotoxic T lymphocyte-associated antigen-4 (CTLA-4) have achieved early success in clinical trials, inducing durable remission in various tumor types." (PMID 36845103, 2023). "Preclinically, the treatment of mice bearing OC with either anti-CTLA4 or its ligand CD80 was shown to slow down the tumor growth and reduce T-cell suppression by MDSC through direct cell–cell interaction." (PMID 37513979, 2023). "This antitumor effect was reported to be further enhanced when cryoablation was used in combination with CTLA-4 antibody, with up to 80% of mice becoming tumor-free." (PMID 36761748, 2023). "In tumor, we found that the expression of tumor ploidy, CTLA4, PD1, and B7-1 was significantly higher in patients with recurrence versus those without recurrence, but there was no statistical significance found in immune score." (PMID 37313417, 2023). "Immune checkpoint proteins, including cytotoxic T-lymphocyte-associated protein 4 (CTLA4), programmed death (PD-1), and programmed death ligand 1 (PDL-1), also play critical roles in immune suppression, especially anti-tumor immunity." (PMID 37242454, 2023). "Correlation analysis of tumor clinical features revealed that CTLA4 expression significantly correlated with T stage (p < 0.001), tumor grade (p < 0.01), M stage (p < 0.01), primary tumor site (p < 0.01), HPV status (p < 0.05) and radiotherapy (p < 0.05)." (PMID 37798374, 2023). "Similar results were observed in another study, where anti-CTLA4 significantly accelerated T cell motility within the tumor." (PMID 38313431, 2023). "Since the combination of DSP-0509 and anti-PD-1 antibody enhanced anti-tumor activity, we next evaluated the anti-tumor activity of the combination with anti-CTLA-4 antibody, a different immune-checkpoint blocker from the anti-PD-1 antibody used clinically." (PMID 36793737, 2023). "This inhibited our ability to evaluate to which extent prior treatment with CPI therapy influence the intact tumor fragments with anti-CTLA-4 and anti-PD-1 blocking antibodies." (PMID 37359554, 2023). "Several anti-CTLA-4 therapies have been developed and approved for the treatment of various types of cancer, and these agents can slow down tumor growth clinically." (PMID 37376141, 2023). "For example, TACE has been shown to induce an immunogenic cell death with tumor-specific immune responses that can be boosted by anti-CTLA-4 treatment." (PMID 38275827, 2023). "Of the checkpoint blockade antibodies, anti-CTLA-4 applied as monotreatment induced a tumor growth delay on the primary as well as the distant tumor and, consequently, on the total tumor burden that outperfomed AU-011 as a monotreatment." (PMID 36997666, 2023). "Tumour cells also activate immunological checkpoint receptors such as cytotoxic T-lymphocyte antigen-4 (CTLA-4) and programmed cell death receptor-1 (PCDR-1)." (PMID 37443570, 2023). "A notable correlation was observed between risk score and expression of CTLA4, HAVCR2, PDCD1, PDCD1LG2, and TIGIT, indicating risk scores represent tumor-induced immunosuppression." (PMID 37404760, 2023). "Since the first U.S. Food and Drug Administration (FDA) approval of ipilimumab, a CTLA-4 monoclonal antibody, in 2011 for the treatment of metastatic melanoma, ICIs have transformed the treatment landscape across multiple tumour types." (PMID 38263984, 2023).
tumor (continued). "Molecular analysis revealed that NK cells became exhausted as they infiltrated across the tumor model, showing higher levels of PD-1, CTLA-4, or IDO-1 and downregulating prosurvival and activation genes such as GZMB or BCL-2." (PMID 38106674, 2023). "Mice that had previously achieved complete remission following dual IRE + anti-CTLA-4 therapy were also 100% protected from secondary tumor challenge." (PMID 37251920, 2023). "More importantly, treatment with plant-produced anti-CTLA-4 reduced the tumor size and repressed the tumor weight comparably with the mammalian cell produced anti-CTLA-4 (Yervoy®)." (PMID 37711295, 2023). "Another clinical study has demonstrated that a high-affinity and selective A2AR inhibitor, ZM241385, in combination with anti-CTLA-4 mAb inhibited tumor growth and enhanced antitumor immune responses in a B16F10 mouse melanoma model." (PMID 36829496, 2023). "INV322 targets CD25 and CTLA-4 on Tregs with lower-affinity monovalent interactions, supporting the selective blockade of tumor-restricted Tregs function and depletion by Fc-mediated clearance." (PMID 37441075, 2023). "The most studied receptors which prevent the destruction of the tumor cells by inhibiting T-cell activity are programmed cell death receptor 1 (PD1) and cytotoxic T-lymphocyte-associated antigen 4 (CTLA4)." (PMID 36675137, 2023). "Under photothermal stimulation, HA-PANI/R837 nanoparticles targeted tumor cells, facilitated the binding of anti-CTLA-4 antibody to R837, and then activated immunogenic cell death." (PMID 37860188, 2023). "Previous studies have demonstrated that combinational therapy of PD-1 and CTLA-4 blockade is more effective than monotherapy in preclinical mouse tumor models and clinical trials." (PMID 37208329, 2023). "Here we showed that canagliflozin and anti-CTLA-4 also synergistically activated T cells in a tumor xenograft model and retarded tumor growth." (PMID 36594471, 2023). "Immune checkpoint genes including CTLA4 and PD-L1 played an important role in regulating the immune response to tumor, and ICB therapy has been widely used to control tumor development." (PMID 38097680, 2023). "A notable association was observed across risk score and the expression of CTLA4, HAVCR2, PDCD1, PDCD1LG2, and TIGIT, indicating risk scores represent tumor-induced immunosuppression." (PMID 37404760, 2023). "Combination therapies that target both CD47 and other immune checkpoints, such as PD-1 and CTLA-4, are also being studied to enhance anti-tumor immunity." (PMID 38188674, 2023). "allowed for the precise and potent release of cytotoxic T lymphocyte-associated protein-4 (CTLA-4) and programmed cell death-ligand 1 (PD-L1), resulting in a significant increase in the therapeutic efficacy for tumor regression." (PMID 37201117, 2023). "Blocking the interaction between the checkpoints and the ligands by an ICI (anti-PD-L1, anti-PD-1, or anti-CTLA-4) allows the CTLs to regain activity and recover their ability to kill the tumor." (PMID 37020242, 2023). "APC-mediated B7 signaling is critical for anti-PD-1/CTLA-4/Ly6C treatment mediated tumor regression." (PMID 37449205, 2023). "The French authors provided post hoc analyses of data from three prospective trials that enrolled patients with different tumor types and were treated with anti-PD-1/PD-L1 agents or their combination with anti-CTLA-4 monoclonal antibodies." (PMID 37754504, 2023). "The accumulation of adenosine will increase the expression of CTLA4 and adenosine receptor 2A (A2AR) on Tregs, promote Treg proliferation and enhance tumor‐associated macrophage (TAM) differentiation into the M2 inhibitory phenotype." (PMID 36807772, 2023). "Among the many immunotherapeutic strategies, immune checkpoint inhibitors have shown great benefits in the treatment of a range of cancer types, such as the use of CTLA-4 and PD-1 or PD-L1 to enhance anti-tumor immunity." (PMID 37118734, 2023).
tumor (continued). "Anti-PD-1, anti-CTLA4, or a combination of the two, have shown tumor reduction and increased survival in HER2/neurogenetic breast cancer models in clinical trials." (PMID 36810560, 2023). "A higher tumor TIDE prediction score was associated not only with poorer response to ICIs therapy, but also with poorer patient survival under anti-PD1 and anti-CTLA-4 therapies." (PMID 37175461, 2023). "Early-stage (stages 1 and 2) tumor tissues had higher numbers of CTLA-4-positive tumor cells compared to late stage (stages 3 and 4)." (PMID 37107632, 2023). "The immune checkpoints PD-1 and CTLA-4 are also involved in inhibiting the anti-tumor response of CAR-T cells." (PMID 37296906, 2023). "Contrary to CTLA-4 action on early T-cell activation, PD-1 affects the response of T cells at the effector stage in the tumour microenvironment." (PMID 38136332, 2023). "In a mouse xenograft model using MC38 colon adenocarcinoma cells, H. pylori-infected mice showed significantly larger tumor volume compared to uninfected mice upon anti-CTLA-4 treatment." (PMID 35914737, 2023). "Treg cells inhibit the activation of anti-tumor T cells by producing immunosuppressive cytokines and immunosuppressive CTLA4." (PMID 37795220, 2023). "Here, using a hierarchy of computational techniques, we design a cyclic peptide that binds CTLA4 and follow this with experimental verification of binding and biological activity, using bio-layer interferometry, cell culture, and a mouse tumor model." (PMID 37122540, 2023). "Ipilimumab and Tremelimumab, therapeutic antibodies blocking CTLA-4, have shown durable control of tumor growth in some patients." (PMID 37881432, 2023). "Combination therapy with anti-PD-L1 and anti-CTLA4 increased effector T cell and F4/80+ macrophage populations in tumor draining lymph nodes of a transgenic murine model, and combination therapy also protected against tumor re-challenge in a syngeneic model." (PMID 37426669, 2023). "Tregs play a crucial part in the immune response, as shown by the fact that Treg depletion restored anti-CTLA-4 capabilities in tumor reduction even in B7x+ mice." (PMID 37842234, 2023). "Along with immune cells, tumor cells also express CTLA4, induced by tumor cell-intrinsic b-catenin signaling." (PMID 37197667, 2023). "In CMS5 inoculated control, Tregs increased the expressions of CD39, CTLA4, and latency-associated protein (LAP) 7 days post tumor challenge, suggesting the enhanced suppressive function of Tregs." (PMID 37407600, 2023). "A significant gradual increase in terms of PD1, TIGIT, and CTLA-4 expression, as evaluated singularly or in co-expression, was observed with the transition to NT and tumor site." (PMID 37898752, 2023). "Lastly, our results show that USP5 inhibition combination with Trametinib or CTLA-4 blockade has an additive role in suppressing the tumor growth." (PMID 37208329, 2023). "The comparison of co-expression of checkpoint molecules between the different ROIs illustrated higher levels of CD4 with CTLA-4 in the sclerotic tumor compared to the interface (p = 0.02)." (PMID 36980192, 2023). "In metastatic lung cancer patients responding to treatment with focal radiation and anti-CTLA4 we have observed a rapid expansion of tumor-specific T cell clones in the peripheral blood." (PMID 37620372, 2023). "In a syngeneic OC mouse model, combining decitabine and anti-CTLA-4 therapy dramatically inhibited tumor progression and extended survival when compared to either drug used alone." (PMID 37368179, 2023). "PD1, PDL1 and CTLA4 are the most representative immune checkpoint pathways, which are closely related to tumor immune escape." (PMID 37803063, 2023). "ICIs targeting CTLA-4 and the PD-1/PD-L1 axis strengthen anti-tumor immune responses by disrupting co-inhibitory T-cell signaling." (PMID 38136311, 2023).
tumor (continued). "By blocking key receptors involved in the T-cell-mediated immune response, such as programmed cell death protein-1 (PD-1), its ligand (PDL-1) or cytotoxic T-lymphocyte-associated protein 4 (CTLA4), an innate immune system-mediated tumor therapy is achieved." (PMID 37374207, 2023). "One study of measles viruses engineered to express anti-CTLA-4 showed a better effect in controlling tumor growth, while the survival effects were similar between viruses expressing anti-CTLA-4 or anti-PD-L1 antibodies and the control group." (PMID 38169820, 2023). "Compared with the anti-PD-1/CTLA-4 treatment alone, the anti-PD-1/CTLA-4 treatment plus TMDCs was significantly more potent in suppressing the tumor growth and inducing cytokines from tumor-infiltrating effector T cells and dendritic cells." (PMID 37449205, 2023). "Early research revealed that AK104 has promising anti-tumor effectiveness in liver cancer and a better safety profile than co-administering anti-PD-1 and anti-CTLA-4 mAbs." (PMID 37441075, 2023). "In some clinical trials, a tumor vaccine is combined with an anti-CTLA-4 monoclonal antibody for treating TNBC." (PMID 36765522, 2023). "Some studies argued that anti-CTLA-4 antibodies produces anti-tumor effect by killing Tregs through antibody-dependent cell-mediated cytotoxicity because Fc domain is essential for ipilimumab anti-tumor function." (PMID 36895477, 2023). "Exhausted CD8+ T-cells (PDCD1+CTLA4+) and Tregs (TIGIT+CTLA4+) were abundant in the tumor and expressed the inhibitory marker LAYLIN (LAYN)." (PMID 37511228, 2023). "Next, we examine the influences of the blocking rate of CTLA-4 to the tumor size on day 18 by fixing the amount of oncolytic virus at s=2×106 and only varying the CTLA-4 blocking rate u." (PMID 36766849, 2023). "Cytotoxic T lymphocyte-associated protein 4 (CTLA-4) plays a crucial role in immune tolerance and has been strongly implicated in anti-tumor immune responses." (PMID 36831449, 2023). "PD-1/PD-L1 and CTLA-4 are inhibitory adaptive immune checkpoint molecules hijacked by many tumor types to suppress T cell-mediated tumor killing." (PMID 37958404, 2023). "In another example in prostate cancer, IRE and anti-CTLA-4 increased intratumoral tumor-specific T cells and increased tissue-resident CD8+ memory T cells (TRM) in non-lymphoid tissues including skin." (PMID 37251920, 2023). "Immune checkpoint inhibitors (ICIs), including PD-1, PD-L1, and CTLA-4 inhibitors, can reactivate the anti-tumor response of the innate immune system by blocking the inhibitory immune checkpoint receptors present in TME or on tumor cells." (PMID 37880277, 2023). "Nevertheless, eliminating tumor granulocytic MDSCs combined with dual checkpoint blockade of PD-1 and CTLA-4 allowed the reduction of even very large tumors." (PMID 37373091, 2023). "ICIs, such as PD-1, PD-L1, and CTLA-4 antibodies, have been shown to promote the activity of potent T-cells and inhibit immunosuppression in the tumor microenvironment." (PMID 36975415, 2023). "ICIs, functioning through interrupting the suppressive signals transduced by CTLA4 or PD1 to reactivate the anti-tumor immunity and prevent tumor immune evasion, was approved to be successful in the treatment of multiple cancers." (PMID 36816030, 2023). "Currently, immune checkpoint molecules of cytotoxic T-lymphocyte-associated antigen 4 (CTLA-4) and programmed cell death receptor (PD-1), as the most promising tumor immunotherapies, have received more attention in clinical applications." (PMID 36917087, 2023). "Autologous CLDN6-CAR-NK cells were engineered to express CCL19/IL7 and scFv targeting PD-1/CTLA-4/Lag-3 to increase the anti-tumor efficacy against CLDN6-positive solid tumors." (PMID 37371075, 2023). "Around 52.2% of patients with moderately differentiated tumours had a positive expression of CTLA-4 (p = 0.01)." (PMID 37761948, 2023).
tumor (continued). "In THCA tumor, CTLA4 (rho = 0.691), HAVCR2 (rho = 0.610), TIGIT (rho = 0.641), VTCN1 (rho = 0.618) showed remarkably positive with FAP expression." (PMID 37166418, 2023). "To date, the exact mode of action of anti-CTLA-4 antibodies and the role of tumor cell-intrinsic CTLA-4 expression with regard to response to ICB is only inadequately understood." (PMID 37415208, 2023). "As previously stated, ICB blocks inhibitory receptors such as PCDR-1/PCDL-1 and CTLA-4 to enable the effector immune cells to kill tumour cells." (PMID 37443570, 2023). "We first examined the expression of PTGS2 and CTLA4 in normal and tumor tissue samples for diverse types of cancer, employing the TNMplot tool of the KMplotter web platform." (PMID 38201508, 2023). "ICI act on PD-1, CTLA-4, and PD-L1 receptors activating the T-cell leading to the killing of the tumor cells." (PMID 38057847, 2023). "The upregulation of inhibitory receptors, such as PD-1 and CTLA-4, on T cells leads to suboptimal activation and, thus, impaired anti-tumor activity." (PMID 37511431, 2023). "Taken together, multiple factors contribute to the immunosuppressive tumor microenvironment and resistance to anti-PD-1/CTLA-4 treatment." (PMID 37449205, 2023). "We co-cultured T cell-treated BCSCs-231 cells (BCSCs-231-T cells) with CD8+ T cells to explore the Role of TN-BCSCs/CTLA4 axis in tumor immunosuppression." (PMID 37838657, 2023). "Decitabine (a related DNMT inhibitor) stimulated the cytotoxic and infiltration responses of CD8+ T cells, which combined with anti-CTLA-4 antibody exhibited synergistic anti-tumor effects and extended survival in a syngeneic murine ovarian cancer model." (PMID 37386520, 2023). "CRT upregulation in tumors improves the tumor infiltration of leukocytes to aid cancer immunotherapy with ICIs (e.g., anti-CTLA-4)." (PMID 37376141, 2023). "The binding of CD80/CD86 on antigen-presenting cells to CTLA-4 on T-cells in the tumor microenvironment suppresses the immune system, enabling tumor proliferation." (PMID 37511453, 2023). "Our study demonstrates that monocytes, a myeloid cell subset, are recruited into inflamed tumor tissues and proliferate after anti-PD-1/CTLA-4 treatment, where they can mediate suppressor roles or rapidly differentiate to dendritic cells upon Ly6C blockade." (PMID 37449205, 2023). "Studies on murine tumor models highlighted the noteworthy anticancer potential of CTLA-4 blockade, which led to the promotion of anti CTLA-4 antibodies." (PMID 36829496, 2023). "Radiation therapy (RT) increases tumor response to CTLA-4 inhibition (CTLA4i) in mice and in some patients, yet deep responses are rare." (PMID 37620372, 2023). "Immune checkpoint blockades with anti-PD-1 or anti-CTLA-4 mAbs restore the glycolytic capacities and reinvigorate the effector functions of TILs in a mouse tumor model." (PMID 36776832, 2023). "For instance, CD80 is activated by CTLA-4, and the transfection of human tumor cells with CD80 prevents PD-L1-mediated immunosuppression by tumor cells and restores T cell function." (PMID 37686682, 2023). "By loading these biological agents in biomaterials designed to inhibit PD-1 and CTLA-4 to some extent, it was possible to reverse the tumor microenvironment (TME) and further trigger the endogenous immune response." (PMID 38312512, 2023). "On the other hand, we found a significant correlation between the CTLA-4 mRNA expression level in CTCs and the tumour stage (T)." (PMID 37761948, 2023). "TMB and MSI, in addition to tumor PD-L1, PD-1, and CTLA4 expression levels, had emerged as potential biomarker possibilities." (PMID 37251370, 2023). "Studies have shown that histone deacetylase (HDAC) makes cancer cells sensitive to ICIs therapy by up-regulating the expression of CTLA-4, PD-1, PD-L1, and PD-L2 on tumor cells and tumor infiltrating lymphocytes (TILs)." (PMID 38155974, 2023).